APOE (apolipoprotein E)
Diseases named in the same sentence as APOE in open-access papers (continued):
Sharing a sentence is not in itself a finding about the gene and the disease.
Stroke (continued). "However, long-term APOE ε2 overexpression in human brains should be carefully evaluated and raises concerns since the APOE ε2 allele is associated with a higher risk for other diseases like CAA and stroke." (PMID 36703235, 2023). "The impact of the APOE genotype in other neurodegenerative diseases characterized by overt inflammation, e.g., alpha- synucleinopathies and Parkinson's disease, traumatic brain injury, stroke, amyotrophic lateral sclerosis, and multiple sclerosis, is also addressed." (PMID 36153580, 2022). "However, in our study we observed no age-specific protective or harmful effects of APOE polymorphism on MI or stroke." (PMID 35332187, 2022). "Further detailed studies on APOE genotyping in more young stroke patients and on whether this SNP information from other possible genotypes may increase the likelihood of the early identification of those vulnerable to post-stroke aspiration pneumonia during their recovery period are warranted." (PMID 36005151, 2022). "Minor APOE alleles seemed not to exert a similar influence on urinary or gastrointestinal tract infections, both of which may increase after stroke due to immunodepression." (PMID 36005151, 2022). "We excluded participants who were lost to follow-up (n = 755), who had missing APOE genotype data (n = 76), who carried the APOE E2/E4 genotype (n = 53), and those with previous MI (n = 146), previous stroke (n = 98) and further missing MI (n = 52) and stroke (n = 64) data alone." (PMID 35332187, 2022). "The association between CCA-IMT and incident stroke was not modified by APOE allele status." (PMID 35332187, 2022). "Thus, the ABCA1/ApoE/HDL signaling pathway may provide a new clinical strategy for improving neurological functional recovery after stroke." (PMID 32575457, 2020). "However, there was a significant interaction between stroke and APOE ε4." (PMID 20576093, 2010). "Thereby, we can not firmly say whether any association of the apoE gene with stroke is independent of lipid levels." (PMID 11434425, 2001). "The APOE gene was investigated in 56% of TBI studies, 52% of stroke studies, and 43% of studies on other brain injuries." (PMID 41476008, 2026). "Of the studies included in this review, APOE was investigated in 34 of 57 (60%) of all TBI studies, 34 out of 46 74% of stroke studies, and 6 of 19 32% of studies on other injuries." (PMID 41476008, 2026). "To date, limited research has explored the relationship between circulating ApoE levels and CVD outcomes, such as stroke and CHD." (PMID 41465167, 2025). "CELSR2, ABO, LPA, APOE, FGF5 and ZPR1 were related to both CHD and HF, while SH2B3 and FURIN were shared between CHD and stroke on MR analysis." (PMID 39322770, 2024). "Moreover, our simulation analyses suggest that a plausible explanation of the association of this locus with stroke AAO can be entirely explained by survival bias, an explanation that is entirely consistent with the robust association reported by multiple studies of the APOE locus with lifespan." (PMID 39286457, 2024). "Genetic polymorphisms were also found to affect the levels of brain-derived neurotrophic factor (BDNF), dopamine, and apolipoprotein E (APOE), which in their turn affect neuroplasticity, functional recovery, and the type of stroke." (PMID 37041905, 2023). "However, neither APOE E2 allele nor E4 allele was associated with incident MI or incident stroke." (PMID 35332187, 2022). "Moreover, ApoE−/− Fbn1C1039G+/− mice develop advanced atherosclerotic lesions with human-like features such as large necrotic cores, intraplaque (IP) neovessels, IP hemorrhages, IP inflammation, and spontaneous plaque rupture leading to myocardial infarction and stroke." (PMID 35625752, 2022). "And intracerebral administration of ApoE and HDL in the knocked down ABCA1 stroke mice remarkably improved axonal myelination." (PMID 34436325, 2021).
Stroke (continued). "Our data indicate that the ABCA1/ApoE/HDL signaling pathway contributes to myelination and oligodendrogenesis in the ischemic brain after stroke." (PMID 32575457, 2020). "Previous study demonstrated that the deletion of brain ABCA1 significantly reduces brain ApoE and HDL content, and it decreases myelin density and OLs and OPCs in the ischemic brain after stroke." (PMID 32575457, 2020). "Although ApoE2 increased brain ApoE/HDL levels and GM/WM density, negligible functional improvement was observed in ABCA1-floxed-stroke mice." (PMID 30373276, 2018). "Both the ABCA1fl/fl stroke mice administered with ApoE2 and ABCA1−B/−B stroke mice administered with ApoE2 exhibited significantly increased ApoE and HDL levels in the CSF 14 days after distal middle-cerebral artery occlusion (dMCAo) (p < 0.05, n = 9/group)." (PMID 30373276, 2018). "However, ApoE2 administration in ABCA1−B/−B stroke mice significantly increased brain ApoE and HDL levels and improved neurological function, which indicates that supplementation of ApoE2 reverses brain ABCA1 deficiency-induced neurological deficits after stroke." (PMID 30373276, 2018). "Impairment as assessed using the National Institutes of Health Stroke Scale (NIHSS), and disability as measured using the modified Rankin Scale (mRS), were compared against the ApoE genotype." (PMID 29390290, 2017). "Bone marrow transplantation from ApoE-/-CD36-/- (mostly expressed in monocytes) donor mice to ApoE-/- recipient mice decreased infarction volume and neurological deficits after stroke." (PMID 24398220, 2014). "At the time of this study, in the HuGENet, there were 13 meta-analyses for the APOE gene, and CAD and stroke." (PMID 22649614, 2009). "Apolipoprotein E (APOE) and elastin (ELN) are plausible candidate genes involved in the pathogenesis of stroke." (PMID 17672902, 2007). "After adjustments for potential confounders, such as age, education level, initial stroke severity, BMI, alcohol consumption, and the Fazekas scale, our findings did not reveal a significant association between ApoE ε4 and PSCI at 3 or 12 months post-stroke." (PMID 40349252, 2025). "A lower education level was consistently associated with the development of subsequent PSCI, whereas age, stroke severity, and ApoE ε4 were not." (PMID 40349252, 2025). "Recent meta-analysis data have implied that common genetic pathways may be a factor in the comorbidity of MDD and stroke, specifically methylenetetrahydrofolate reductase (MTHFR) and apolipoprotein E (ApoE) genes." (PMID 37456466, 2023). "For APOE ɛ4 carriers who have not had a stroke, predictors of resilience were increased frequency of mild physical activity and being employed at baseline for men, and increased number of mental activities engaged in at baseline for women." (PMID 37198167, 2023). "Participants with incident MCI at t2 were significantly older, had lower education levels, were more often APOE ε4 carrier and had more often a positive history of stroke than participants without incident MCI." (PMID 36386784, 2022). "Since L-4F can cross the BBB and reach the CNS, to further elucidate whether L-4F treatment-induced neurorestorative effect on T2DM-stroke is mediated by ABCA1 and ApoE signaling pathway, ABCA−B/−B mice were employed." (PMID 35572941, 2022). "The evidence suggests that BDNF and APOE loci are involved in recovery from TBI or stroke, but recent GWAS studies in stroke recovery have failed to implicate either." (PMID 33479258, 2021). "Here, we investigate whether ABCA1/ApoE/HDL contribute to myelin repair and oligodendrogenesis in the ischemic brain after stroke." (PMID 32575457, 2020).
Stroke (continued). "Previous studies have found that the intracerebral administration of human ApoE2 into ABCA1fl/fl stroke mice significantly elevated the brain level of ApoE and HDL and increased gray/white matter density and neurogenesis, as well as improved neurological functional outcome after stroke." (PMID 32575457, 2020). "In this study, using ABCA1-B/-B mice, we further investigate whether ABCA1, ApoE, and the HDL signaling pathway mediate axonal myelination and contribute to oligodendrogenesis and WM remodeling in the ischemic brain after stroke." (PMID 32575457, 2020). "In addition to inflammatory and oxidative stress, apolipoprotein E was also shown to regulate transporter abundancy and localization at the BBB in an experimental stroke model." (PMID 31915017, 2020). "Thirdly, we were not able to identify the pre-stroke condition or apolipoprotein E (APOE) genotype of the patients, which might have a potential impact on cognition, though we screened the pre-stroke cognitive conditions using IQCODE." (PMID 39949537, 2025). "A previous study in Zambia found an increased risk of haemorrhagic stroke in individuals with the ApoE ε2ε4 genotype, but correlations with plasma ApoE levels were not investigated, and no evaluations on the association with HIV or young-onset stroke were made." (PMID 41541874, 2025). "APOE genotype may modify the relationship between NLR and 3-month stroke outcome." (PMID 36640294, 2023). "In addition, among APOE ε4 carriers, high NLR was associated with the increased risk of stroke-related disability, however, no such relationship was observed among APOE non-ε4 carriers." (PMID 36640294, 2023). "Thus, if plaque rupture occurs in ApoE−/−Fbn1C1039G+/− mice, this will not always give rise to occlusive thrombi that provoke MI or stroke." (PMID 35008828, 2021). "Studies of APOE ε4 in stroke have mainly focused on stroke incidence rather than outcome, although emerging evidence suggests that the ε4 allele may have a detrimental effect on poststroke recovery." (PMID 27242654, 2016). "We found that although ApoE2 administration increased brain levels of ApoE and HDL in ABCA1fl/fl stroke mice, significant improvement in functional outcome was not evident." (PMID 30373276, 2018). "This study along with previous studies suggests that L-4F derived therapeutic effects in brain rewiring after stroke injury may, at least partially, be independent of the ABCA1, ApoE, or ApoA-I." (PMID 35572941, 2022). "Additionally, 75% of patients with recurrent stroke had a combined APOE ε2ε3 and ACE I/D genotype, whereas in the pediatric group without recurrent stroke, it was only 6%." (PMID 31906461, 2020).
depression (317 papers, 2008 to 2026). "Upon activation with CNO (3 mg/kg), behavioral assays demonstrated that the targeted activation of hippocampal GABAergic neurons partially ameliorated the depression-like behaviors caused by ApoE knockdown." (PMID 40530388, 2025). "Age, female sex, APOE ε4, depression, MMSE, and CFI scores were associated with higher amyloid burden." (PMID 40476544, 2025). "Collectively, these findings demonstrate that ApoE knockdown results in impaired GABAergic synaptic function and pronounced depression-like behaviors, which highlights the pivotal role of ApoE in regulating hippocampus-associated behaviors." (PMID 40530388, 2025). "Moderation analyses of diet scores on the relationship between symptoms of depression and anxiety on brain Aβ in the cohort as a whole and stratified by APOE ɛ4 allele carriage." (PMID 40775676, 2025). "DR, depression and APOE E4 positive were associated with higher prevalence of AD both in the univariate and multivariate GLM (Model 2) adjusted by age (all p<0.001)." (PMID 40778276, 2025). "Those who were APOE ε4 allele carriers had higher Depression-Behavior (b = 0.253, p = 0.04, 95% CI [0.012, 0.493]) scores than non-carriers." (PMID 40217501, 2025). "In conclusion, we delved into the underlying mechanisms by which ApoE influences depression-like behaviors." (PMID 40530388, 2025). "In humans, an association between ApoE gene polymorphism and susceptibility to depression has been reported." (PMID 40026711, 2025). "Lastly, we employed chemogenetic and pharmacological approaches to investigate the underlying mechanisms by which ApoE regulates GABAergic transmission and depression-like behaviors." (PMID 40530388, 2025). "Apolipoprotein E (ApoE) has been implicated in neurodegenerative diseases; however, its function and underlying mechanisms in depression remain elusive." (PMID 40530388, 2025). "In both genders, DM, APOE E4, and depression were all associated with higher prevalence of AD in both univariable and multivariable GLM adjusted by age (all p<0.05)." (PMID 40778276, 2025). "In both genders, DM, carrying APOE E4 and depression were all associated with a higher prevalence of AD in both univariate and multivariate GLM adjusted by age (all p<0.05)." (PMID 40778276, 2025). "The association between genetic status (GBA1 and APOE ε4 carrier status) and the four Neuropsychiatric dimensions (depression, anxiety, adult stress-adversity, ASRB) was assessed using mixed-effects models." (PMID 41326418, 2025). "In older EA Veterans who reported lower levels of PTSD and depression symptomatology, we observed an association between APOE ε4 and SCC." (PMID 38951900, 2024). "Depression and the apolipoprotein E ε4 allele had an association with memory impairment and reduced has-miR-107, a prominent risk marker for early AD." (PMID 39092642, 2024). "Recent longitudinal studies employing a large population have also shown apparent risk effects of ApoE*ε4 for increased depressive symptomology and incident depression status." (PMID 38506067, 2024). "A meta-analysis on the association between APOE genotype and depression found that in a Caucasian population, the E2 allele likely acted as a protective factor for depression, while the E44 and E43 genotypes acted as risk inducers." (PMID 38673634, 2024). "This remained true when adjusting for additional covariates including education, ApoE risk, recent depression and lifestyle factors." (PMID 37037939, 2023). "Other studies have shown that there is an association between depression and a number of genotypes of the APOE gene." (PMID 37763074, 2023). "Several studies have shown that certain genotypic polymorphisms in the APOE gene coding region are risk factors for depression and other diseases." (PMID 37763074, 2023).
depression (continued). "One of the risk factors for depression is the APOE gene, a number of variants of which have been associated with the development of atherosclerosis and cardiovascular disease, as well as with the development of neurodegenerative disorders and brain pathology." (PMID 37763074, 2023). "The aim of the study was to investigate the association of the APOE gene polymorphism with depression in the white adult population aged 25–64 years in Novosibirsk (Western Siberia)." (PMID 37763074, 2023). "Further exploration into the potential association between biomarkers, risk genes (e.g., APOE), and stress and stress-related biomarkers (such as cortisol and astrocyte-derived markers) and depression, are warranted." (PMID 37779209, 2023). "The meta-analysis was a review of 398 sources of information on the association between the ε4 allele of the APOE gene and depression." (PMID 37763074, 2023). "A meta-analysis of 20 studies showed an association between a polymorphism in the APOE gene and a predisposition to depression." (PMID 37763074, 2023). "Possible pathophysiological mechanisms for the development of depression in carriers of the ε4 allele of the APOE gene include impaired regulation of lipid metabolism, as well as immune–inflammatory imbalance and increased oxidative stress." (PMID 37763074, 2023). "The current findings indicated that APOE-ε4 was associated with not only AD (p < 0.0001) but also with anxiety (p < 0.0001) and depression (p = 0.0004)." (PMID 37510309, 2023). "The ε4 allele of the APOE gene was statistically significantly associated with depression: OR = 1.360, 95% CI 1.110–1.660, p = 0.003, in the dominant model: OR = 1.340, 95% CI 1.060–1.680, p = 0.001." (PMID 37763074, 2023). "A high frequency of the ε4 allele of the APOE gene was found in patients with depression and the ε4 allele was a risk factor for depression." (PMID 37763074, 2023). "None of the miRNAs were directly associated with verbal memory score, APOE ε4 status, or depression (all p-values > 0.01)." (PMID 35884866, 2022). "Secondly, we additionally examined the potential role of circulating plasma miRNAs to gain first insights into epigenetic regulators of depression, the APOE ε4 allele, and memory impairment." (PMID 35884866, 2022). "The APOE ε4 allele was highly significant over represented and associated with HH and depression in DLB patients." (PMID 36123648, 2022). "NACC data investigation showed that sleep disturbance, depression as well as APOE genotype are associated with subsequent diagnosis of AD dementia." (PMID 35197840, 2022). "APOE ε4 allele is thought to be implicated in microglial responses and it has been identified as a risk factor for depression and AD." (PMID 35379792, 2022). "The APOE ɛ4 allele was associated with depression in mild-moderate DLB after adjusted several confounders." (PMID 36123648, 2022). "Julian and co-authors conducted a study to elucidate the association of the APOE gene with depression, which often occurs in patients with MS." (PMID 35885971, 2022). "Their results concluded that the APOE ε2 allele shows a protective effect by reducing the incidence of depressive disorders." (PMID 35885971, 2022). "In the present study, we confirmed that APOE ε4 allele exacerbated depression-like behaviors in mice during aging." (PMID 34611141, 2021). "Our study shows that the presence of factors, such as older age, low education, cardiovascular risk factors, and depression, are associated with aMCI and naMCI independently of the APOE e4 allele carrier status." (PMID 33430178, 2021). "Population-based studies reveal that apolipoprotein E (APOE) ε4 gene allele is closely associated with late-life depression (LLD)." (PMID 34611141, 2021). "Given the mixed evidence regarding APOE e4 as a risk factor for later-life depression, further research is needed to replicate these findings." (PMID 33648619, 2021).